CGAS (cyclic GMP-AMP synthase)
Diseases named in the same sentence as CGAS in open-access papers (continued):
Sharing a sentence is not in itself a finding about the gene and the disease.
Obesity (continued). "Both mitochondrial DNA and oxidized DNA activate cGAS‐STING in adipocytes and macrophages during obesity." (PMID 39158380, 2025). "In this review, we summarize the current knowledge on the roles of TLR9, cGAS‐STING, AIM2, IFI16, DNA‐PK, and DDX41 in obesity, diabetes, fatty liver disease, and cardiovascular disease." (PMID 39158380, 2025). "The overexpression of cGAS and STING provokes innate immune dysregulation and pathological processes during diabetes or obesity." (PMID 39891248, 2025). "Inhibiting cGAS or STING has the potential to mitigate inflammation and improve metabolic outcomes in diseases such as obesity, insulin resistance, and NAFLD." (PMID 39669992, 2024). "c-MYC induces DNA damage and increases ROS levels by activating the cGAS-STING signaling pathway, as observed in obesity and metabolic syndrome." (PMID 38813101, 2024). "Inhibiting the cGAS-STING signaling pathway reversed metabolic dysfunction, ameliorated insulin resistance, decreased body weight and obesity, and reduced inflammation, and fibrosis observed in the untreated NAFP group." (PMID 36915161, 2023). "Here, we established an obesity-related DCM mouse model and observed the presence of cytosolic mtDNA, activation of cGAS/STING, and its downstream targets during DCM." (PMID 35235096, 2023). "Involvement of cGAS/STING signaling in the periphery in metabolic dysfunction, such as obesity and prediabetes/diabetes is well-documented." (PMID 37206668, 2023). "Our study demonstrated that lipotoxicity-induced mtDNA release led to cardiac cell death and fibrosis by activation of cGAS-STING signaling and subsequent inflammation in the obesity-related DCM mouse model." (PMID 35235096, 2023). "Meanwhile, in the context of high-fat diet, fat can specifically overexpress DsbA-L or inhibit the cGAS–STING signaling pathway to promote fat thermogenesis and protect mice from high fat-induced obesity." (PMID 35536585, 2022). "The individual pathophysiological role c-Myc, cGAS/STING, IDO1, and AHR plays in inflammatory responses has been demonstrated in obesity and type 2 diabetes 69-71." (PMID 35154484, 2022). "This suggested that the activation of cGAS-STING signaling pathway in both adipocytes and macrophages contributes to obesity-induced adipose inflammation and metabolic disorder." (PMID 34943809, 2021). "Conversely, fat-specific overexpression of DsbA-L or suppression of the cGAS–STING pathway promoted PKA signaling-dependent beige and brown fat thermogenesis, protecting mice from HFD-induced obesity." (PMID 32444826, 2020). "The activation of the cGAS–STING pathway promoted inflammation and exacerbated obesity or DsbA-L knockout-induced insulin resistance in mice, thereby uncovering an important mechanism linking immunity and metabolism." (PMID 32444826, 2020). "In the current study, we demonstrate that activation of the cGAS–STING pathway inhibits beige and brown fat thermogenesis, contributing to increased obesity in the DsbA-LfKO mice." (PMID 32444826, 2020). "We found that MORC3, NUP62, CGAS, ABI3, and RPA2 were highly expressed in lean individuals, where as LMNA, ID2, CDKN1A, TENT4B, MME, and MYC were upregulated in the PBMCs of individuals with obesity." (PMID 40847086, 2025). "In addition, during obesity, gut-derived microbial DNA can also be translocated to the liver and is expected to activate macrophage STING through cGAS-cGAMP signaling." (PMID 36937350, 2023). "We found here that neither obesity nor inflammation affected cGAS and STING expression levels in adipocytes." (PMID 37830559, 2023). "The developmental stage of adipocytes, obesity status and inflammatory signals did not correlate with the expression of the cGAS/STING pathway in the adipose tissue." (PMID 37830559, 2023).
Obesity (continued). "In this study, with an obesity-related DCM mouse model established by feeding db/db mice with a high-fat diet (HFD), we observed increased mtDNA in the cytosol and activated cGAS-STING signaling pathway during DCM, as well as the downstream targets, IRF3, NF-κB, IL-18, and IL-1β." (PMID 35235096, 2023). "In addition, mitochondrial dysfunction or abnormal activation of cGAS-STING under metabolic stress can also induce more common diseases, such as obesity, obesity-induced inflammation, insulin resistance, etc." (PMID 37100799, 2023). "Recent studies show that also self-DNA may activate cGAS-STING, for instance, DNA released from nuclei or mitochondria during obesity or myocardial infarction." (PMID 34381828, 2021). "Mitochondrial and oxidized DNA activate cGAS‐STING in adipocytes and macrophages, exacerbating inflammation and reducing thermogenesis, while the downstream kinase TBK1 plays a dual role by inhibiting energy expenditure during obesity and suppressing inflammation during nutrient deprivation." (PMID 39158380, 2025). "Overall, the cGAS‐STING signaling pathway intricately intersects with various aspects of energy homeostasis and metabolic regulation, significantly contributing to the pathophysiology of obesity, adipose tissue inflammation, and insulin resistance through multiple mechanisms." (PMID 39158380, 2025). "Cytosolic mtDNA stimulation of the cGAS-STING pathway was observed in adipocytes 28, the endothelium 29, 30 and cardiomyocytes 31, thereby regulating inflammation, macrophage infiltration, insulin resistance, atherosclerosis and obesity-induced diabetic cardiomyopathy." (PMID 38164186, 2024). "In recent years, numerous studies have shown that the cGAS-STING signaling pathway plays a pivotal role in the prevention and treatment of metabolic diseases, and this pathway may be a new target to combat metabolic diseases such as obesity and T2DM." (PMID 37762143, 2023). "Prior studies examining the role of cGAS/STING signaling in HFD-induced obesity and metabolic dysfunction have primarily used STING, and not cGAS, knockout mouse models." (PMID 37206668, 2023). "This suggests that cGAMP may activate the negative feedback system of the cGAS-STING pathway, thus reducing obesity-induced chronic inflammation." (PMID 38312740, 2024). "Consistent with a negative role of adipose cGAS‒STING signaling in regulating thermogenesis, adipose-specific knockout of TBK1 attenuates HFD-induced obesity by increasing energy expenditure, which has been attributed to increased AMPK activity that enhances catabolism." (PMID 34665236, 2021).
COVID-19 (49 papers, 2020 to 2025). A disease caused by infection with severe acute respiratory syndrome coronavirus 2. "Severe COVID-19 and long COVID are also linked to increased expression of cGAS and STING genes, along with elevated plasma IFN-α." (PMID 41227273, 2025). "As SARS-CoV-2 induces COVID-19 in humans, and is linked to the activation of the cGAS-STING pathway triggered by mtDNA, we analyzed mtDNA levels in the blood of SARS-CoV-2-infected patients." (PMID 39375263, 2024). "Recently, the cyclic GMP-AMP synthase (cGAS)–stimulator of interferon genes (STING) pathway was implicated in the pathological type I IFN responses in COVID-19." (PMID 35663932, 2022). "Moreover, cGAS–STING activity was detected in lung samples from patients with COVID-19 with prominent tissue destruction, and was associated with type I IFN responses." (PMID 35045565, 2022). "Likewise, in lung samples from patients with COVID-19 with prominent tissue destruction, cGAS–STING activity was associated with type I IFN responses." (PMID 35663932, 2022). "Moreover, cGAS-STING activity was detected in lung samples of COVID-19 patients with prominent tissue destruction and associated with type I IFN responses." (PMID 35336077, 2022). "In this scenario, inhibitors targeting cGAS-STING or cell fusion may suppress inflammation-associated disorders in COVID-19 patients." (PMID 34732709, 2021). "During the pathogenesis of severe COVID-19, disrupted mitochondrial homeostasis in vascular endothelial cells adjacent to the infection sites causes the accumulation of mtDNA in the cytoplasm, which initiates the cGAS-STING-IFN I response and the ultimate cell death." (PMID 37122745, 2023). "Despite advancements in understanding the role of cGAS-STING signaling in COVID-19 and its potential therapeutic applications, several challenges remain." (PMID 40072090, 2025). "In particular, patients with severe COVID-19 show an overactive inflammatory response that is in part mediated by the cGAS-STING pathway." (PMID 40868819, 2025). "Patients with severe COVID-19 exhibit a hyper-inflammatory response with an activation of the NF-kB response, which is mediated by the cGAS-STING pathway." (PMID 40868819, 2025). "Patients with severe COVID-19 exhibit a hyper-inflammatory response (the cytokine storm) that is in part mediated by the cGAS-STING pathway." (PMID 40868819, 2025). "In acute COVID-19, cGAS, STING, IFN-α, TNF-α, and IL-6 levels were higher in patients with severe disease than in those with nonsevere manifestations (p < 0.05)." (PMID 38424312, 2024). "A bioinformatics analysis of the single-cell and bulk RNA-seq profiling of COVID-19 patients’ data revealed a significant upregulation of cGAS-STING signalling pathway genes (TMEM173, IRF3, NFKB1, CGAS, IFNAR1, and TBK1) in the lung." (PMID 39459875, 2024). "The activation of endothelial cGAS and IFN-I signaling appears to be closely linked to COVID-19-related cognitive deficits." (PMID 37941028, 2023). "Cyclic GMP-AMP synthase-stimulator of interferon genes (cGAS–STING) pathway is an important regulator of peculiar Type 1 IFN responses to COVID-19." (PMID 37051070, 2023). "A present study unveils that HERV-K (HML-2) stimulates interferon via cGAS/STING in COVID-19 patients." (PMID 36769337, 2023). "demonstrate that cGAS-STING-activated IFN I response is prominent in the damaged lung tissues of severe COVID-19 patients." (PMID 37122745, 2023). "Recently, it was reported that the upstream signal molecule of STING, cGAMP, which is an immune-stimulating molecule produced by cGAS, can be used as an adjuvant of the COVID-19 vaccine." (PMID 36569852, 2022). "Our results of undetectable cGAS expression in villous tissue and fetal membrane from COVID-19 placentas suggest that STING activation in villous and decidual stromal cells is cGAS-independent." (PMID 36743911, 2022).
COVID-19 (continued). "The cGAS–STING pathway has a central role in the pathogenesis of severe COVID-19 by driving the increase in type I interferons that occurs in the later stages of SARS-CoV-2 infection." (PMID 35045565, 2022). "Recently, cGAS-STING activity has emerged as regulator of immunopathology in COVID-19, highlighting the relevance of adequate STING regulation." (PMID 35933402, 2022). "Concerning cGAS-STING signaling, in both infected cell cultures and COVID-19 patient samples, a specific activation of NF-κB mediated by cGAS-STING recruitment was described and supported by its attenuation after treatment with several STING-targeting drugs." (PMID 35336077, 2022). "We propose that more consideration be paid to the dysregulated IFN-I release in COVID-19 and that cGAS and STING be considered therapeutic targets for avoiding cytokine storms and as critical components in host antiviral defense mechanisms." (PMID 36457340, 2022). "Finally, it will be important to assess the degree to which cGAS inhibition diminishes morbidity and mortality in patients with COVID-19." (PMID 40220296, 2025). "SARS-CoV-2, which caused the COVID-19 pandemic, is an RNA virus and is, thus, not directly recognized by the cGAS-STING pathway." (PMID 40868819, 2025). "Moreover, studies on human samples showed that cGAS-STING pathway participates in the response of endothelial cells towards SARS-CoV-2 infection as well as in driving type I IFN responses in COVID-19 skin lesions." (PMID 41139159, 2025). "Conversely, in severe or late-stage COVID-19, cGAS-STING pathway antagonists may offer therapeutic benefits." (PMID 40072090, 2025). "Moreover, in a recent study involving 148 individuals, including 87 with acute COVID-19 and 61 in the post-COVID-19 period, increased cGAS and STING gene expression, along with elevated IFNα levels, were associated with long-term COVID-19." (PMID 40431629, 2025). "The gene expression levels of cGAS, STING and the plasma levels of the cytokines IFN-α, TNF-α and IL-6 in patients with acute COVID-19 were evaluated according to factors considered risk factors for the severity of the disease, namely, sex, age and comorbidities." (PMID 38424312, 2024). "Activation of the cGAS-STING pathway may contribute to an intense systemic inflammatory state in severe COVID-19 and, after infection resolution, induce an autoinflammatory disease in some tissues, resulting in long COVID." (PMID 38424312, 2024). "Thus, the present study aimed to investigate the association between the severe form of acute COVID-19 and long COVID with the gene expression of STING and cGAS and the plasma levels of IFN-α, TNF-α and IL-6." (PMID 38424312, 2024). "Moreover cGAS is activated in endothelial cells by mtDNA released in the cytoplasm, as observed in lung-on-chip model and in skin biopsies from COVID-19 patients." (PMID 37077526, 2023). "Notably, macrophages isolated from COVID-19 patients were found to engulf dying cells, resulting in activation of the cGAS-STING pathway." (PMID 37253946, 2023). "Our research strongly supports our idea that HERV-K (HML-2) activation in COVID-19 patients might promote cGAS-STING pathway activation and regulate the SUMO pathway and β-defensin production, thus inducing IFN-I production." (PMID 35632738, 2022). "Consistent with previous reports in patients with COVID-19 (ref.26), endothelial cells in our LoC studies contain viral elements, arguing for direct viral involvement in triggering mitochondrial dysfunction and, in turn, the activity of the cGAS–STING pathway." (PMID 35045565, 2022). "Injured DNA spread into the cell's cytosol during the late stages of COVID-19 may stimulate the cGAS-STING molecular signalling pathway, leading to a severe cytokine storm in specific individual." (PMID 36457340, 2022). "Targeting the cytoplasmic chromatin-cGAS-STING pathway may offer novel therapeutic opportunities in treating COVID-19." (PMID 34732709, 2021).
COVID-19 (continued). "Therefore, syncytia formation may underlie the inflammatory response associated with cGAS-STING signaling, potentially impacting COVID-19 disease severity and symptoms." (PMID 41305428, 2025). "Furthermore, the cGAS-STING pathway induces IFN-I-mediated immunopathology in COVID-19." (PMID 41226461, 2025). "Thus, the cGAS-STING pathway plays a crucial role in the progression of COVID-19." (PMID 40072090, 2025). "Thus, the cGAS–STING pathway is a crucial driver of type I IFN responses in COVID-19 skin lesions." (PMID 35045565, 2022). "Cases of severe COVID-19 in very young children suggest that some genetically encoded, and perhaps not yet described, gain of function mutations of the cGAS-STING pathway could be a first explanation for severe SARS-CoV-2 infections in the young." (PMID 33335532, 2020). "Among them, twelve are literature reviews primarily exploring how the cGAS/STING pathway influences the progression and severity of COVID-19, with potential therapeutic implications." (PMID 40072090, 2025). "Cyclic GMP-AMP synthase (cGAS)–stimulator of interferon genes (STING) pathway controls immunity to cytosolic double-stranded (ds)DNA, driving aberrant type I IFN responses in COVID-19 patients." (PMID 40416961, 2025). "There is increasing evidence supporting the role of the cGAS/STING pathway, a DNA sensor, on the pathogenesis of SARS-CoV-2 infection and progression of COVID-19." (PMID 40072090, 2025). "In acute COVID-19, TNF-α, IFN-α, STING and cGAS showed a performance that varied from fair to good in differentiating severe and non-severe cases, with area under the curve (AUC) ranging from 0.7051 to 0.8145 (p < 0.05)." (PMID 38424312, 2024). "In assessing the correlation between the gene expression levels of cGAS, STING and cytokines in acute COVID-19, a positive correlation was observed between the levels of all markers in the group with the severe form of the disease." (PMID 38424312, 2024). "A heatmap was constructed for joint analysis of the gene expression levels of cGAS and STING and plasma levels of IFN-α, TNF-α and IL-6 in acute COVID-19 and in the post-COVID-19 period." (PMID 38424312, 2024). "Evaluation of cGAS and STING gene expression levels showed that the group with the severe form of acute COVID-19 had higher levels of cGAS (p = 0.0009) and STING (p = 0.0269)." (PMID 38424312, 2024). "The cGAS-STING pathway, which controls immunity to cytosolic DNA, is a critical driver of aberrant type I IFN responses in COVID-19." (PMID 38195584, 2024). "After that, binding with the angiotensin-converting enzyme 2 (ACE2) receptor, in part activates the cGAS-STING pathway and related IFN-I response, which can contribute to worsening the COVID-19 severity." (PMID 38831299, 2024). "Our study shows that engagement of the cGAS–STING pathway regulates two distinctive pathological features that are critically involved in the progression and severity of COVID-19—namely, endothelial dysfunction and type I IFN production." (PMID 35045565, 2022). "It shows a similar mechanism that activates the cGAS-STING pathway in both endothelial cells and macrophages in COVID-19 lesions." (PMID 36457340, 2022). "In many patients with severe COVID-19, SARS-CoV-2 infection induces the secretion of highly pro-inflammatory cytokines through cGAS-STING and NF-κB-mediated signaling." (PMID 35933402, 2022). "It is important to emphasize that cGAS-STING pathway activation may influence vaccine efficacy, as cGAMP is utilized as an adjuvant in intranasal COVID-19 vaccines to enhance the immune response." (PMID 40072090, 2025). "The link between VDAC1 and SARS-CoV-2 was demonstrated, by the overexpression of VDAC1 in a population of T cells, suppression of mtDNA release, cGAS-STING pathway activation and improved survival in the T cells of COVID-19 patients when treated with the VDAC1-interacting compound VBIT-4." (PMID 39375263, 2024).